MMP9 (matrix metallopeptidase 9)
Diseases named in the same sentence as MMP9 in open-access papers (continued):
Sharing a sentence is not in itself a finding about the gene and the disease.
tumor (continued). "The angiogenic function of TEMs in hypoxic tumor sites may be related to its secretion of VEGFA, MMP-9 and so on." (PMID 26599011, 2015). "PCR analysis of control (SAH) and experimental (SAM) treated LM-7 cells showed a marked inhibition in the expression of tumor-promoting genes (MMP-2, MMP-9, VEGF, PAI-1, and uPA) and genes (uPA, TFG-β, and RUNX2) which are known to promote the development and progression of skeletal metastasis." (PMID 25619880, 2015). "Tumor-promoting factors (CXCR4, MMP-9, NF-κB) were significantly increased in the proliferating and invasive compared to the adherent cells, however HCT116R cells overexpressed factors in comparison to the parental HCT116, suggesting an increase in malignancy behavior." (PMID 25884903, 2015). "In addition, MMP-9 was found to be upregulated in the epithelial component in KCOT and to play a vital role in angiogenesis and tumor invasion as well as in bone resorption in KCOT." (PMID 25879017, 2015). "The important point of our study was that tumor MMP-9 positivity was not determined by a scoring system but by the presence or absence of tumor MMP-9 expression." (PMID 25888323, 2015). "An IHC staining score of 10 (range, 0-300) was used to divide patients into 2 groups, according to the presence or absence of tumor MMP-9 expression." (PMID 25888323, 2015). "Also TANs in melanoma or fibrosarcoma tumors expressed high levels of MMP-9 and VEGF, and elimination of these TANs resulted in reduced tumor growth." (PMID 26819959, 2015). "It’s notable that inhibition of tumor-derived (human) MMP9 alone was not as effective in metastases reduction as dual targeting of both tumor and stromal MMP9, while inhibition of stroma-derived MMP9 (mouse) was as effective as dual targeting." (PMID 25961845, 2015). "We suggest that the anti-tumor properties of DATS may beneficial for the inhibition of metastasis by down-regulating the activities and expression of ERK/NF-κB /MMP-2/MMP-9." (PMID 25927362, 2015). "Subsequently, MMP-9 was found overexpressed in the tumor tissue (identified by GFP staining) and not MMP-2 (data not shown)." (PMID 26588686, 2015). "The preponderant phenotype observed in tumor stroma is a tumor promoting phenotype characterized by the expression of molecules promoting angiogenesis (e.g., VEGF-C, IL-8), tumor growth (TNF-α) and invasiveness (MMP-7, MMP-9)." (PMID 31557983, 2015). "Stress selectively increased MMP9 expression in tumor cells (~50-fold compared to non-stressed mice) while stress enhanced MMP2 expression in cells from the stromal compartment (>100-fold compared to non-stressed mice)." (PMID 26193320, 2015). "Moreover, MMP-9 mainly regulates the bioavailability of VEGF, the most potent inducer of tumor angiogenesis." (PMID 26597177, 2015). "When these pathologies were grouped as AN, the difference in the corrected MMP-9 levels compared to no neoplasia became near significance (p-value = 0.056)." (PMID 26264519, 2015). "The results demonstrated that tumor MMP-9 expression was not a significant independent prognostic predictor for DFS (p = 0.142), whereas LVI, stage, and tumor histology were significant independent prognostic variables." (PMID 25888323, 2015). "The major MMPs involved in tumor angiogenesis are MMP-2 and MMP-9." (PMID 26597177, 2015). "Tumor invasion requires the secretion of proteolytic enzymes by tumor cells to break down the extracellular matrix (ECM) proteins (e.g., collagen, fibronectin and laminin), with the matrix metalloproteinases (MMPs) MMP-2 and MMP-9 playing a major role." (PMID 25874926, 2015). "Our study reveals that EMP3 contributes to tumor aggressiveness by MMP-9 and uPA, but not MMP2, on the PI3K/AKT pathway in HCC cells." (PMID 26472188, 2015). "These authors show that MMP-9 promotes SHH signaling and tumor growth indirectly by cleaving SERPINE2/PN-1 and propose that increasing its levels may be critical for blocking malignant progression of prostate cancer." (PMID 25901736, 2015).
tumor (continued). "Patient 3 had high PAI-2 and low MMP-9 IHC expression levels and was alive and had no tumor recurrence at the final follow up." (PMID 26230665, 2015). "Glaucine also dose-dependently inhibited the enzymatic activity of MMP-9 secreted from PMA-induced MCF-7 cells, suggesting that it is a strong candidate for decreasing tumor metastasis and invasion via dual inhibition of MMP-9 gene transcription and enzyme activity." (PMID 25670016, 2015). "Regardless of the reduced number of neoplasia cases, we found that corrected MMP-9 levels were increased in stage II and III patients compared to stage I patients." (PMID 26264519, 2015). "Because MMP2/9 play important roles in tumor invasion and metastasis, FAK contributes to the invasion and metastasis of HCC partly through regulating expression and activation of both MMP-2 and MMP-9." (PMID 26068982, 2015). "In the case of MMP9, here we clearly showed that the major sources for MMP9 were M2MΦ, rather than M1MΦ, or non-macrophages in LC tissue that included LC cells, tumor endothelial cells, mesenchymal cells, and non-macrophage leucocytes." (PMID 25961789, 2015). "The secreted levels of MMP-9 or VEGF-C expression were upregulated in TE-1 or ECA 109 cells treated with IL-23 compared to control, suggesting that the IL-23 might contribute to tumour metastasis." (PMID 25721268, 2015). "It was further demonstrated that OPN itself could induce MMP9 and VEGF in a dose dependent manner, and all three proteins co-localized in PDAC cells as well as in patient tumor samples from smokers." (PMID 26264026, 2015). "This procedure showed distinct bands of both latent and active MMP-9 in tumor extracts but vague bands in non-tumor extracts." (PMID 24778099, 2014). "Moreover, EGF is one of the growth factors that lead to VEGF and MMP-9 expression, crucial mediators for tumor angiogenesis and invasion in the RCC microenvironment, therefore facilitating the spread of tumor cells." (PMID 25909813, 2014). "Here, we suggest that HSPB1 is primarily secreted from tumor endothelial cells, not tumor cells and cleavage of soluble HSPB1 by MMP9 leads to endogenous anti-angiogenic effects during tumor progression." (PMID 24465581, 2014). "VEGF induces gelatinase B/MMP-9 expression in vascular cells and some malignant tumour cell types." (PMID 24473089, 2014). "Baseline plasma MMP-9 concentration, Karnofsky performance score, type of tumor, and grade of tumor among the groups were not significantly different." (PMID 24397933, 2014). "Although S1P signalling promotes angiogenesis, specific signalling through S1P2 in endothelial cells and tumour-infiltrating myeloid cells has a counterbalancing effect, inhibiting tumour angiogenesis and tumour growth in vivo through inhibition of VEGF expression and MMP9 activity." (PMID 24970218, 2014). "The levels of active MMP-9 in our series of PTC tissue extracts were significantly higher in tumor tissues than in non-tumor tissues." (PMID 24778099, 2014). "The authors make note that expression of MMP-9 primarily derives from host immune cells such as neutrophils, macrophages, and mast cells, as opposed to tumor cells." (PMID 24877061, 2014). "There is much evidence demonstrating that MMP-9 is overexpressed in various tumor types when compared to normal tissue." (PMID 24778099, 2014). "Gelatinase B/MMP-9 digests C1q complement component at a site required for interaction with the C1qR02 receptor, repressing C1q/C1qR02 involvement in tumour immunology and may also degrade complement component C1r." (PMID 24473089, 2014). "CAFs promote tumor growth and invasion secreting proangiogenic factors (i.e., VEGF-A and MMP-9), proinflammatory molecules (i.e., SDF-1, IL-6, and IL-1β), and several growth factors (i.e., TGF-β, platelet-derived growth factor, PDGF, and basic fibroblast growth factor, bFGF)." (PMID 25136593, 2014).
tumor (continued). "Interaction between gelatinase B/MMP-9 and CD44 results in EGF receptor activation and signalling through ERK, Akt and FAK, which promotes tumour cell invasion and migration, with FAK coordinating adhesion, polarisation, migration, invasion, survival and death." (PMID 24473089, 2014). "Surprisingly, the reduction in blood vessel density did not appear to correlate with a reduction in tumor growth, as the average tumor weight and ex vivo bioluminescence signal were only slightly lower in the group with tumor cell MMP9 KD (not significant)." (PMID 24811362, 2014). "In our study, there was a significant correlation between MMP-9 expression and lymph node metastases, advanced tumor stage as well as estrogen receptor negative and progesterone receptor negative hormonal status." (PMID 24993803, 2014). "There is no doubt that gelatinase B/MMP-9 plays a fundamental role in tumour biology, ranging from initiation/promotion to angiogenesis, dissemination, immunological surveillance and metastatic growth." (PMID 24473089, 2014). "Conversely, silencing of HOTAIR impaired migration and invasion of EOC cells in vitro, as well as inhibited tumor spread in a mouse model of intraperitoneal metastasis, likely via metalloproteinases (MMP3 and matrix metalloproteinase-9, MMP9) and epithelial-to-mesenchymal pathways." (PMID 24971229, 2014). "Therefore, the treatment with IFN-γ/TNF-α enabled T-sMs to induce anti-tumor function of the neutrophils by increasing the production and/or release of MPO, NE, and TRAIL, and reducing the expression of Bv8 and Mmp9 genes." (PMID 25587026, 2014). "Their patterns of immunostaining, unlike those of MMP-2 and MMP-9, are very likely to afford an indication of the invasion potential of the tumour." (PMID 26019601, 2014). "Tumor invasion can be induced by macrophages through the production of enzymes and inhibitors that regulate the digestion of the ECM, as well as through the production of several MMPs including MMP-1, MMP-2, MMP-7, MMP-9, MMP-12 and MMP-14." (PMID 24578639, 2014). "In addition, matrix metallopeptidase 9 (MMP-9) and vascular endothelial growth factor promotes tumor invasion and angiogenesis." (PMID 24533079, 2014). "We discuss the roles of (pro)-MMP-9 (active and latent forms) and NGAL in tumour development, and evaluate the mechanisms by which pro-MMP-9/NGAL may influence the actions of (pro)-MMP-9 and NGAL in cancer." (PMID 24713998, 2014). "To further test whether solanine can affect tumor metastasis, we determined the level of tumor metastasis related marker proteins, MMP-2 and MMP-9, in Panc-1 and SW1990 cells." (PMID 24949471, 2014). "The tumor-derived exosomes induced the tumor cell to highly express CXCR4 and MMP-9." (PMID 24765179, 2014). "Alternatively, endothelial cell clusters within metastatic sites may be primed to produce gelatinase B/MMP-9 by circulating VEGF through VEGF receptors, which may facilitate tumour cell extravasation across an already compromised vascular BM." (PMID 24473089, 2014). "Furthermore, gelatinase activity in 48h-conditionned serum free media revealed that media derived from control tumor cells presented high MMP-2 and MMP-9 activity." (PMID 24961901, 2014). "The MMP-9 enzyme involved in extracellular matrix remodeling is overexpressed in MTC lesions and may contribute to tumor vascularization and growth." (PMID 24527080, 2014). "An important aspect of EMT is acquisition of higher migration and invasion capacities of tumor cells coupled with increased expression of proteolytic enzymes of the extracellular matrix (ECM) such as gelatinases A and B, MMP-9, MMP-2, and urokinase-type plasminogen activator (uPA)." (PMID 24900952, 2014). "Gelatinase B/MMP-9 is an important regulator of both innate and tumour immune responses." (PMID 24473089, 2014).
tumor (continued). "To invade the cells need an active process that involves cell motility and extracellular matrix proteolysis, and for this reason we monitored the expression of MMP-9, matrix metallopeptidase-9, which belongs to MMP family involved in tumor progression, including invasion and cancer metastasis." (PMID 25380967, 2014). "Although, bone marrow-cell derived gelatinase B/MMP-9 appears to be sufficient for tumour vasculogenesis, it is not essential and can be substituted by gelatinase B/MMP-9 from either stromal, smooth muscle or tumour cell components." (PMID 24473089, 2014). "Enzymes such as MMP-9 degrade ECM and create a microenvironment that maintains tumor development." (PMID 24960186, 2014). "Finally, a growing body of evidence suggests that by binding cell surface receptors, pro-MMP-9 and NGAL can initiate signal transducing events that control tumour cell processes." (PMID 24713998, 2014). "In OSCC, MMP9 serves as a predictor of tumor recurrence when detected in histologically-negative surgical margins of OSCC." (PMID 24466237, 2014). "The results showed that MMP-2 and MMP-9 had similar expression patterns in the tumour cells with no changes in the immunoreactivity during tumour progression." (PMID 26019601, 2014). "Gelatinase B/MMP-9 is considered to be a tuner and amplifier of inflammatory and immune functions and is up regulated by pro-inflammatory cytokines such as TNFα, IL-1β, IL-6 and TGFβ in a wide variety of human tumour cells, stromal and endothelial cells." (PMID 24473089, 2014). "Furthermore, the presence of MMP9-expressing TAM positively correlated with tumor angiogenesis, tumor growth and VEGF-A levels." (PMID 24634660, 2014). "In pancreatic cancer, the overexpression of miR-143 significantly decreased the protein levels of MMP-2 and MMP-9, lowered the constitutive activities of RhoA, Rac1, and CDC42 GTPases, and also significantly inhibited cell migration and invasion of tumor cells in vivo and in vitro." (PMID 24670365, 2014). "Secondly, tumour samples taken from patients were immuno-stained for both IGFBP-3 and MMP-9." (PMID 24905466, 2014). "Leptin promotes tumor growth, eliciting the activity of several signaling pathways such as insulin-like growth factor-1 (IGF-1) and HER2 and inducing the expression of MMP-2, MMP-9, and VEGF, which finally promote cell migration and metastatic spreading." (PMID 25136593, 2014). "Previous studies have shown that NF-kB may be involved in promoting tumor metastasis by regulating cytokines such as TNF, IL, MMP-9, and ICAM." (PMID 24837834, 2014). "Also they are known to participate in angiogenesis and tumor growth particularly gelatinases (gelatinase A, MMP2, gelatinase B, and MMP9)." (PMID 25135219, 2014). "Furthermore, inhibition of integrin ανβ6 markedly downregulated the expression of matrix metalloproteinase-9 (MMP-9), matrix metalloproteinase-3 (MMP-3) and urokinase plasminogen activator (uPA) in tumor conditioned medium." (PMID 25176506, 2014). "This present report describes another molecular level of a novel organizational signaling platform connecting the Snail-MMP-9 signaling axis in amplifying the Neu1 sialidase and MMP-9 cross-talk in regulating EGF receptors, tumor neovascularization, growth and invasiveness." (PMID 26932374, 2014). "M2 TAMs support tumor progression through the release of immunosuppressive (i.e., CCL2 and IL-10), proangiogenic (i.e., IL-8 and VEGF), and tissue remodeling (i.e., MMP-2 and MMP-9) factors." (PMID 25136593, 2014). "Immunostaining of total and active MMP-9 was observed in tumor tissue and occasionally in non-neoplastic epithelium." (PMID 24778099, 2014). "However, MMP2, MMP9 and MMP14 are the three major MMPs reported to be involved in tumor angiogenesis." (PMID 25071013, 2014). "Transcripts of other genes such as matrix metallopeptidase-9, serpin-1 and vascular cell adhesion molecule-1 were not affected in tumor tissue that survived ablation." (PMID 24270800, 2014).
tumor (continued). "MMP-9 expression is low or absent in most normal tissues, and it is markedly elevated during inflammatory, autoimmune, degenerative and neoplastic diseases and angiogenic lesions." (PMID 24392031, 2013). "From the Cox proportional hazards analysis neither the ELISA measurements of MMP-9:TIMP-1 (Q2, Q3, or Q4) nor menopausal status, tumor size, lymph node status, or malignancy grade were associated with DFS." (PMID 24330623, 2013). "On the basis that astrocyte-secreted MMP-2 and MMP-9 partially mediated tumor cell invasion in vitro, we investigated whether astrocyte-secreted MMP-2 and MMP-9 are involved in astrocyte CM-induced brain metastasis." (PMID 24324647, 2013). "MMP9 and VEGF were correlated with tumor progression, stimulating tumor growth and metastasis." (PMID 23946779, 2013). "In addition, from the immunological point of view, it was reported that pharmacological inhibition of MMP9 by aminobisphosphonate decreased pro-MMP9 and VEGF in the serum and abrogated the induction of MDSC in the tumor microenvironment." (PMID 23606867, 2013). "As MMP-9 plays an important role in tumor metastasis, gelatinase activity (indicating the activity of MMP-2 and MMP-9) was assessed by in situ zymography, which is a unique technique for revealing proteolytic activity at specific sites in tissues or cell cultures." (PMID 23862139, 2013). "MMP-9 and PLAU were the most important degradation enzymes of extracellular matrix, while degradation of extracellular matrix was a necessary process during tumor invasion, and metastasis." (PMID 24379889, 2013). "In vivo evidence from chicken chorio-allantoic membrane (CAM) assay shows that MMP-9 is inter-dependent in tumor invasion, while tumor cells show only low levels of invasion in the absence of MMP-9." (PMID 24053256, 2013). "Thus, our in vivo data further confirm a functional contribution of GM-CSF overexpression to tumor invasion and malignancy, together with the upregulation of collagenolytic and gelatinolytic activities by enhanced expression of MMP-2, MMP-9, and MMP-26." (PMID 23634280, 2013). "Gelatinase B (matrix metalloproteinase-9, MMP-9) is a secreted multidomain enzyme that is important for the remodeling of the extracellular matrix and the migration of normal and tumor cells." (PMID 23351884, 2013). "In contrast, the reciprocal incubation of U937-derived sups with both TNFα-stimulated tumor cells did not affect MMP-9 secretion, and elevated VEGF secretion by about 2.5-folds (p < 0.001)." (PMID 23874303, 2013). "Also, a non significant difference was reported between the activity of different MMPs with the tumor size except MMP9/TIMP-1, which showed a significant high expression in patients with large tumor size (>5 cm) as compared to low size group (p = 0.032)." (PMID 23672427, 2013). "Furthermore, lycopene and fish oil inhibited tumor progression and inflammation through suppression of MMP-7, MMP-9, COX-2, and PGE2." (PMID 23970935, 2013). "Furthermore, MMP-9 and to a lesser extend MMP-2 sequester VEGF, required for the initiation of tumor angiogenesis." (PMID 23634280, 2013). "Finally, soluble EMMPRIN enhanced monocytic secretion of MMP-9 and VEGF, as inhibition of its expression levels by neutralizing anti-EMMPRIN or siRNA in the tumor cells lead to subsequent decreased induction of these two pro-angiogenic proteins." (PMID 23874303, 2013). "Increased expression of MYB found in the tumor vs mets comparison (logFC 1.2) may also contribute to MMP1 down-regulation; Myb protein is known to up-regulate cathepsin D and MMP9 and down-regulate MMP1." (PMID 23405235, 2013). "Furthermore, LEF1 knockdown reduced tumor cell viability, invasion capacity, MMP2 and MMP-9 expression, but induced apoptosis." (PMID 24098538, 2013).